AHI1 (Abelson helper integration site 1)
Description:
Involved in vesicle trafficking and required for ciliogenesis, formation of primary non-motile cilium, and recruitment of RAB8A to the basal body of primary cilium. Component of the tectonic-like complex, a complex localized at the transition zone of primary cilia and acting as a barrier that prevents diffusion of transmembrane proteins between the cilia and plasma membranes. Involved in neuronal differentiation. As a positive modulator of classical Wnt signaling, may play a crucial role in ciliary signaling during cerebellum embryonic development.
Synonyms: AHI-1; FLJ20069; ORF1; JBTS3; dJ71N10.1
Tractability: PROTAC: ubiquitination databases record sites on it; its protein half-life has been measured.
Gene: Protein-coding gene on chromosome 6 (135,283,407 to 135,498,434, reverse strand). Ensembl gene ENSG00000135541.
Subcellular location: Cytoplasm, cytoskeleton, cilium basal body; Cell junction, adherens junction; Cytoplasm, cytoskeleton, microtubule organizing center, centrosome, centriole
Subcellular location (Human Protein Atlas): Centrosome; Primary cilium
Pathways (Reactome):
Organelle biogenesis and maintenance: Anchoring of the basal body to the plasma membrane
Gene Ontology:
Molecular function: identical protein binding; protein binding
Biological process: cilium assembly; cell surface receptor protein tyrosine kinase signaling pathway; intracellular protein localization; motile cilium assembly; negative regulation of apoptotic process; photoreceptor cell outer segment organization; positive regulation of receptor internalization; positive regulation of transcription by RNA polymerase II; protein localization to ciliary transition zone; regulation of behavior; vesicle-mediated transport
Cellular component: adherens junction; cell-cell junction; centrosome; ciliary basal body; cilium; centriole; ciliary transition zone; cytosol; MKS complex; non-motile cilium
Genetic constraint (gnomAD): Loss-of-function variants: 98 observed, 108.38 expected, observed/expected ratio (o/e) 0.9, 90% interval 0.77 to 1.07. The upper end of that interval is the gene's LOEUF score, 1.07, which puts it in group 4 of 6, group 1 being the genes least tolerant of losing a copy. Missense variants: 1,233 observed, 1,211.2 expected, observed/expected ratio (o/e) 1.02, 90% interval 0.97 to 1.07. Synonymous variants: 426 observed, 403.94 expected, observed/expected ratio (o/e) 1.05, 90% interval 0.97 to 1.14.
Gene-disease validity (ClinGen):
ClinGen rates the evidence that AHI1 causes each of these diseases.
Joubert syndrome 3 (autosomal recessive): Definitive. Any Joubert syndrome in which the cause of the disease is a mutation in the AHI1 gene.
Homologues: Orthologues: chimpanzee AHI1 (98% identical), macaque AHI1 (94% identical), rabbit AHI1 (85% identical), dog AHI1 (82% identical), pig AHI1 (81% identical), mouse Ahi1 (70% identical), rat Ahi1 (69% identical), zebrafish ahi1 (42% identical), tropical clawed frog ahi1 (41% identical). Paralogues in human: TEP1 (11% identical), MAPKBP1 (10% identical), WDR62 (10% identical), WDR17 (9% identical), WDR81 (8% identical), WDR7 (8% identical), WDR27 (7% identical), NWD1 (7% identical), SNRNP40 (7% identical), WDR75 (7% identical), POC1B (7% identical), WDR43 (7% identical), and 14 more.
Diseases named in the same sentence as AHI1 in open-access papers:
AHI1 is named in the same sentence as 75 diseases in open-access papers, as found by Europe PMC text mining. Sharing a sentence is not in itself a finding about the gene and the disease. The quoted sentences say what the papers report.
Joubert syndrome (45 papers, 2006 to 2025). Joubert syndrome (JS) is characterized by congenital malformation of the brainstem and agenesis or hypoplasia of the cerebellar vermis leading to an abnormal respiratory pattern, nystagmus, hypotonia, ataxia, and delay in achieving motor milestones. "AHI1 is crucial for brain development: its mutation leads to Joubert syndrome, characterized by cerebellar and brainstem malformations, as well as symptoms like breathing irregularities, hypotonia, developmental delays, and ocular motor apraxia." (PMID 40242760, 2025). "The AHI1 gene plays a key role in brain development, and mutations in AHI1 can lead to Joubert syndrome, a rare autosomal recessive disorder characterized by abnormal brain development and mental retardation." (PMID 36691038, 2023). "Rare biallelic mutations in AHI1 cause Joubert syndrome, a rare monogenic disorder manifesting in agenesis of the cerebellum, ataxia, hypotonia, and intellectual disabilities." (PMID 37547536, 2023). "Several PSGs are associated with Joubert syndrome, including AHI1, CSPP1, and TCTN1, and are essential for cerebellar development." (PMID 33441416, 2021). "For example, KD cells of Ahi1, whose human ortholog is mutated in Joubert syndrome, showed disorganized and decreased actin filaments." (PMID 33972689, 2021). "Even though certain AHI1 variations were previously associated with Joubert syndrome (JS), c.2106G>A (p.(Thr702=)) was only reported in one patient in trans with another known pathogenic JS variant." (PMID 34205586, 2021). "Mutations in the AHI1 (Abelson helper integration site 1) gene are the most common cause of Joubert syndrome." (PMID 33917666, 2021). "In conclusion, we report a patient with a Joubert syndrome phenotype caused by the homozygous c.1739C>T (rs202057391) AHI1 variant for first time in the literature." (PMID 34205586, 2021). "Cerebellar hypoplasia and aberrant foliations in vermian lobules VI and VII have been shown to be associated with defective Wnt/β-catenin signaling in a mouse model of loss of function of Ahi1, a Joubert syndrome-associated gene." (PMID 32000863, 2020). "It has been shown that AHI1 is mutated in patients with Joubert syndrome and its deletion leads to cerebellar hypoplasia presumably by a proliferation deficit." (PMID 33046712, 2020). "On the other hand, a mutation in AHI1 gene is one of the causes of Joubert syndrome characterized by agenesis of the cerebellar vermis, cognitive impairment, and delayed development." (PMID 33046712, 2020). "AHI1 mutations lead to Joubert syndrome, a rare autosomal recessive disorder characterized by an abnormal brain structure, cerebellar hypoplasia, retinal dystrophy, renal degeneration, and delayed development." (PMID 31191667, 2019). "Ahi1 (or Jouberin), which is mutated in Joubert syndrome, regulates the recruitment of Rab8a to the basal body." (PMID 26840332, 2016). "This patient was confirmed to have Joubert syndrome due to a homozygous mutation in AHI1, c.1051C > T (p.R351X)." (PMID 27391121, 2016). "Direct sequencing of the 26 coding exons of AHI1 revealed a homozygous mutation (p.Thr304AsnfsX6) located in exon 7 present in the three Joubert syndrome-affected Moroccan siblings." (PMID 26541515, 2015). "AHI1 is highly expressed in fetal brain and also in the cerebellum and cerebral cortex of the adult brain, and mutations in AHI1 cause Joubert Syndrome." (PMID 24690944, 2014). "A recent study by the Gleeson group provided important insights into the causes of cerebellar phenotypes in Joubert syndrome caused by mutations in AHI1 (Abelson helper integration site 1)." (PMID 24027500, 2013). "A functional role for AHI1 in brain development is suggested by the numerous structural defects associated with Joubert syndrome." (PMID 23028714, 2012). "Ahi-1 deficiency can also cause defective Wnt-dependent cerebellar midline fusion that is critical for the development of Joubert syndrome." (PMID 22248740, 2011).
Joubert syndrome (continued). "Recently, mutations in the human AHI-1 gene have been found to be associated with Joubert syndrome, an autosomal recessive brain disorder." (PMID 22248740, 2011). "In another ciliary disease, Joubert syndrome, one of the causative genes, AHI1, is required for cortical and cerebellar development." (PMID 21698230, 2011). "Altered AHI-1 isoforms and its mutations also underline other diseases, including Joubert syndrome-associated nephronophthisis and autism, and metabolic syndromes." (PMID 22248740, 2011). "Of particular interest, they affected neuronal genes, including Ahi1 (implicated in Joubert syndrome), Tox3 (a calcium-dependent transactivator), and Htr5a (a serotonin receptor), all of which are implicated in neuronal function and psychiatric disorders (57, –59)." (PMID 40802685, 2025). "Mutations in the AHI1 gene could lead to Joubert syndrome, which is a rare genetic disorder characterized by the underdevelopment of cerebellar vermis." (PMID 34950701, 2021). "To date, Cend1 has been shown to interact directly with RanBPM, a promiscuous scaffolding protein of the nervous and immune systems, and Ahi1, a protein implicated in Joubert syndrome, which is a rare autosomal recessive disorder characterized by an abnormal brain structure." (PMID 31191667, 2019). "The AHI1 variant E1086G is a pathogenic mutation in a case of Joubert syndrome." (PMID 24690944, 2014). "Interestingly, Ahi1 has been associated with neurodevelopmental disorders, such as Joubert syndrome, a rare autosomal recessive disorder characterized by abnormal cerebellar development as well as with schizophrenia and autism." (PMID 24312406, 2013). "In addition, AHI-1 isoforms and its mutations also underlie other diseases, including Joubert syndrome-associated nephronophthisis and autism, and metabolic syndromes, including type 2 diabetes." (PMID 22248740, 2011). "Importantly, AHI-1 has recently been identified as a susceptibility gene involved in a number of brain disorders, including Joubert syndrome." (PMID 22248740, 2011). "Therefore, it is likely that AHI-1 mutations are critical in the development of diseases such as Joubert syndrome and specific types of human leukemia." (PMID 22248740, 2011). "Moreover, mutations in AHI-1 have also been associated with Joubert syndrome, an autosomal recessive brain disorder." (PMID 22248740, 2011). "Joubert syndrome (JBTS) is an inherited autosomal recessive disorder associated with cerebellum and brainstem malformation and can be caused by mutations in the Abelson helper integration site-1 (AHI1) gene." (PMID 30949029, 2019). "Nevertheless, as with Joubert syndrome individuals, Ahi1 knockout mice exhibited hypoplasia in lobules VI-VII." (PMID 40538625, 2025). "In Joubert Syndrome, the expression of AHI1 was significantly increased in the crossing axons of corticospinal tract and superior cerebellar peduncle." (PMID 37409103, 2023). "It is reported that kidney disease affects up to 1/3 of patients with Joubert syndrome and is more common in those with pathogenic variants in CEP290, TMEM67 and AHI1 genes." (PMID 35858853, 2022). "In humans, mutations in AHI1 and CC2D2A cause Joubert Syndrome and both genes have been proposed as potential modifiers of CEP290." (PMID 30970040, 2019). "A further five individuals from four families returned a molecular diagnosis consistent with syndromic conditions (CLN3; Batten disease/AHI1; Joubert syndrome / IFT140; Mainzer‐Saldino syndrome) and were referred for clinical re‐evaluation." (PMID 29178642, 2017). "In particular, AHI1 mRNA was expressed in cell bodies of midline-crossing neurons, providing an explanation for axonal abnormalities found in Joubert-syndrome." (PMID 23083465, 2012). "Mutations in AHI1 (Abelson-helper integration site-1) are the most common genetic cause of JSRD, accounting for 12% of cases and 20% of individuals with Joubert syndrome and Leber's congenital amaurosis." (PMID 23028714, 2012).
Joubert syndrome (continued). "As an example, AHI1 was ranked fourth best candidate gene out of 89 genes when UGET was used to retrospectively identify known Joubert Syndrome (JBST) genes." (PMID 20046828, 2009). "Wnt activity is reduced in Ahi1-mutant mice, a model of Joubert syndrome." (PMID 40538625, 2025). "Moreover, the study on a mouse model of Joubert syndrome using Ahi1 knock-out showed that lithium treatment of pregnant dams resulted in a partially restored phenotype in knock-out embryos." (PMID 38036661, 2024). "Authors presented that lithium treatment of pregnant Ahi1 knock-out dams with Joubert syndrome partially restored the normal phenotype (intact midline fusion and increase in the number of proliferating cells) in Ahi1 knock-out embryos compared to the animals not treated with lithium." (PMID 38036661, 2024). "Mutations in AHI1 were initially described in patients with Joubert syndrome and no kidney involvement." (PMID 29379777, 2017). "Mutations in AHI1 and CEP290 are both a frequent causes of Joubert syndrome and genetic variants in both genes may act as modifier alleles, especially in regard to a retinal and CNS phenotype." (PMID 23028714, 2012). "Therefore, it is very likely that truncated forms of AHI-1 are critical in development of diseases such as Joubert syndrome and specific types of human leukemia." (PMID 22248740, 2011). "The same method was subsequently used to unravel the functional modules associated with nine ciliopathy-associated bait proteins, NPHP1–NPHP6, NPHP8, AHI1 and MKS1, identified in the ciliopathies nephronophthisis (NPH), Joubert syndrome (JBTS) and Meckel–Gruber syndrome (MKS) (see Glossary)." (PMID 41164956, 2025). "In a cohort of patients with nephronophthisis and neurological phenotypes consistent with Joubert syndrome (JBTS), half of those with variants in NPHP1 also harboured a second variant, including heterozygous missense variants in AHI1 and truncating variants in CEP290." (PMID 37628633, 2023). "About 30% of patients with Joubert syndrome exhibit ASD30 and conversely, common genetic variation in AHI1 gene is reported in patients with ASD31, suggesting that disruption of AHI1 leads to symptoms of ASD." (PMID 33046712, 2020). "In addition to the role of Ahi-1/AHI-1 in the development of leukemia and lymphoma in mice and humans, studies have also demonstrated its function in brain disorders such as Joubert syndrome (JS) and related disorders (JSRD), schizophrenia and autism." (PMID 22248740, 2011).
ciliopathy (21 papers, 2011 to 2026). A genetic disorder of the cellular cilia or the cilia anchoring structures, the basal bodies, or of ciliary function. "A zebrafish morpholino knockdown model targeting ahi1 enables efficient phenotypic assessment of ciliopathy-related defects and functional evaluation of variants of uncertain significance." (PMID 42116549, 2026). "AHI1 encodes a protein that localizes to primary cilia and is mutated in the rare ciliopathy Joubert syndrome 3 (OMIM #608629), which exhibits multiple neurological phenotypes, including cerebellar vermis hypoplasia and ataxia." (PMID 35140266, 2022). "Overall, to our knowledge, this is the first patient representing a severe ciliopathy phenotype caused by a homozygous synonymous AHI1 variation." (PMID 34205586, 2021). "For example, an allele of RPGRIP1L enhances retinal degeneration across a spectrum of ciliopathies and mutations in AHI1 were suggested to increase the severity of photoreceptor degeneration in nephronophthisis patients." (PMID 30970040, 2019). "Biallelic mutations in the ciliopathy-associated genes AHI1, BBS10, IQCB1, and OFD1 were identified in single patients." (PMID 29974258, 2018). "Upon ahi1 knockdown in zebrafish, we have previously shown hydrocephalus, alongside other defects associated with a ciliopathy." (PMID 23028714, 2012). "ahi1 KO fish models are known to cause ciliopathy and abnormal early development." (PMID 30949029, 2019). "At least two polymorphic markers per gene (rs1718031 and rs729386 for NPHP1; rs1041480 and rs2064430 for AHI1; rs2061589 and rs1508595 for CEP290; rs1990637 and rs1946155 for RPGRIP1L; rs1483457 and rs911 for TMEM67) were inconsistent with linkage in Ciliopathy-672." (PMID 22002901, 2011).
autism (13 papers, 2010 to 2023). Persistent deficits in social interaction and communication and interaction as well as a markedly restricted repertoire of activity and interest as well as repetitive patterns of behavior. "Down-regulation of the expression of the rate-limiting enzyme in dopamine biosynthesis, tyrosine hydroxylase (TH), in AHI1-knockout (KO) mice is responsible for AHI1-deficiency-mediated autism symptoms." (PMID 37200906, 2023). "AHI1 is required for both cerebellar and cortical development in humans and has previously been associated with schizophrenia, autism, and Joubert syndrome-related disorders." (PMID 26479702, 2015). "While the study presented here was designed and performed, three case-control association studies reported the involvement of AHI1 in the susceptibility to schizophrenia and autistic disorder." (PMID 20805890, 2010). "Genetic association has also been reported between AHI1 and autism." (PMID 24690944, 2014). "Furthermore, there is also evidence of an association between an AHI1 haplotype and autistic disorder (ASD) in a region of the gene that had been previously associated with schizophrenia." (PMID 20805890, 2010). "The AHI1-knockout autism mouse model showed low expression of TH and a decrease in dopamine synthesis." (PMID 37200906, 2023). "We also identified PSGs associated with communication disorders, such as autism (CNTNAP4, AHI1, FAN1, SNTG2, and GRIP1) and dyslexia (KIAA0319)." (PMID 33441416, 2021). "Such overlaps are reflected in evidence for Darwinian positive selection, and recent human-specific changes in otherwise conserved amino acid positions, in genes such as AHI1, CNTNAP2 and FOXP2 that have been associated with risk of autism." (PMID 23639054, 2013). "Disrupted in schizophrenia 1 (Disc1), pericentriolar material 1 (PCM-1), and human jouberin (Abelson helper integration site 1 (AHI1)) are linked with schizophrenia, hamartin (Tuberous sclerosis 1 (TSC1)) is linked with autism, and pericentrin (PCNT), DCDC2, and Dyx1c1 are linked with dyslexia." (PMID 28125008, 2017). "Association studies investigating WNT2, DISC1, MET, DOCK4 or AHI1 also provide evidence that the canonical Wnt pathway might be affected in autism." (PMID 23083465, 2012). "Moreover, AHI1 screening in five other patients with CEP290-related disease and neurological involvement revealed a second novel missense variant, p.His758Pro, in one LCA patient with mild mental retardation and autism." (PMID 20683928, 2010).